NR4A1 (nuclear receptor subfamily 4 group A member 1)
Diseases named in the same sentence as NR4A1 in open-access papers (continued):
Sharing a sentence is not in itself a finding about the gene and the disease.
A further 245 diseases each share a sentence with NR4A1 in 4 papers or fewer.